BRCA1 (BRCA1 DNA repair associated)
Diseases named in the same sentence as BRCA1 in open-access papers (continued):
Sharing a sentence is not in itself a finding about the gene and the disease.
cancer (continued). "Furthermore, despite the tissue specificity (breast and ovary) of BRCA1 mutant cancer, a haploinsufficient phenotype was not limited to mammary epithelial cells." (PMID 25400221, 2014). "Using the age matched cohort subset, urinary IL-1β levels were analyzed with respect to a family history of cancer though the BRCA1 status of these patients could not be confirmed." (PMID 25403235, 2014). "Indeed, because BRCA1 is a multi-domain protein involved in a number of key cellular processes, the results of such assays can often be misleading and may even result in inaccurate cancer risk assessment, as they do not take into account the possible impact on the function of the entire protein." (PMID 24695549, 2014). "The BRCA1 expression in the 142 carcinoma samples was as follows, 67 (47.2%) were negative and 62 (43.7%) were weakly positive, nine (6.3%) were moderately positive and four (2.8%) were strongly positive for BRCA1." (PMID 24944674, 2014). "A second issue regarding PARP inhibitor associated therapy is that even if there is an observed sensitivity to PARP inhibitors in cancer cells without functional BRCA1, the difference is much smaller compared with the difference reported previously on pre-cancerous cells." (PMID 23388117, 2013). "The E3 ligase activity of the heterodimer is not affected by mutations in BARD1, whereas the cancer associated C61G missense mutation, which removes the conserved zinc-binding cysteine from the RING domain of BRCA1 completely abolishes the ubiquitin ligase activity of the heterodimer." (PMID 24832651, 2013). "Interestingly, high RAD21 expression correlated with poorer survival in BRCA2 (P = 0.006) and BRCAX cancers (P = 0.008), but not in BRCA1 cancers (P = 0.71)." (PMID 22537934, 2012). "For example, to access information about the BRCA1 (breast cancer 1, early onset), GSTP1 (glutathione S-transferase pi) and ESR1 (estrogen receptor 1) gene methylation profile across various types of cancer, a user could input BRCA1, GSTP1, ESR1 as search terms separated by line breaks." (PMID 22168213, 2011). "Importantly, it has been suggested that some BRCA1/2 carriers will not develop cancer during their lifetime, although the identification of such individuals is currently impossible." (PMID 20961453, 2010). "About 90% of BRCA1 related cancers are ER negative and/or PR negative with weak HER2 expression." (PMID 19818148, 2009). "Given that the addition of mammography to CE MRI did not result in any additional cancer detected in the BRCA1 group, the cost-effectiveness could only be computed for the comparison of CE MRI to mammography alone." (PMID 17016484, 2006). "BRCA1 could be characterized as having a basal phenotype, ER-negative and HER2-negative, with up-regulation of cyclin A and caspase 3, but downregulation of cyclin D1 and D3, CDKIs (p16, p21, p27), and BCL2, the opposite phenotype from most BRCA2 carcinomas." (PMID 16595007, 2006). "However, in our study the overall percentages of ER-negative cancers were much lower for both groups (67% among BRCA1 and 19% among unselected controls)." (PMID 15642173, 2005). "No other variable differed significantly from non-BRCA1/2 cancers." (PMID 15642173, 2005). "An attractive hypothesis to be tested in clinical studies will be whether also methylation of BRCA1 in a significant fraction of sporadic breast and ovarian cancers, and possibly of FANC-F in breast tumours, can determine the response of such cancers to treatment with cross-linking drugs." (PMID 15054444, 2004). "In addition, PARPi is not eligible to treat cancer patients carrying normal BRCA1/2." (PMID 40299557, 2025).
cancer (continued). "Moreover, olaparib can be exploited for other types of cancer, regardless of BRCA1 status." (PMID 41155174, 2025). "However, there is some evidence that cancer biology is different in BRCA1 carriers compared to non-carriers, with BCRA1 carriers having lower or higher and BRCA2 carriers having higher survival rates, which would result in an over- or under-estimation of the ICER, respectively." (PMID 37365514, 2023). "Since MC180295 could suppress the expression of BRCA1 and BRCA2, DNA damage response for double-stranded DNA breaks was disrupted in the MC180295-treated EBVaGC cells, indicating that the combination of MC190285 and a PARP inhibitor might lead to cancer-cell-specific death." (PMID 36142506, 2022). "Furthermore our study depicted an improved OS in patients non-BRCAmut HRD supporting the hypothesis that non-BRCAmut HRD and possibly BRCA1 promotor methylated EOCs are an important subset of cancers with impaired HRR." (PMID 36497449, 2022). "However, HR-deficient cells lacking BRCA1 or BRCA2 show specific susceptibility to PARP1 inhibition, whereby accumulation of genetic lesions and ensuing chromosome instability in fast-dividing cancer cells results in their death." (PMID 35018214, 2022). "However, actionable genes such as BRCA1 and BRCA2 also harbor a myriad of genetic variants of unknown clinical significance (VUSs) hampering prevention and cancer management efforts, especially in African American (AA) women who report a higher frequency of VUS in BRCA1/2." (PMID 36315513, 2022). "For example, cells with mutations in BRCA1 or BRCA2 cannot perform DNA double-strand break (DSB) repair by homologous recombination (HR), and accumulate genetic lesions through alternate use of nonhomologous end joining (NHEJ) that directly leads to cancer development." (PMID 35018214, 2022). "However, how BRCA1 and CK2 interplay to regulate cancer-related events remains unknown." (PMID 35292711, 2022). "In the case of tumor cells with deficiency in BRCA1 or BRCA2, loss of CSB expression would also predict that these cancer cells would not be able to depend upon BIR for survival and might turn to different salvage repair pathways such as alternative end joining, which in turn could be targeted." (PMID 36142121, 2022). "Thus, our study not only identifies BARD1 mutations affecting the BRCA1/BARD1 complex but also uncovers the synergetic effect of cis mutations in individual genes on tumorigenesis, which updates the understanding of how non-effective mutations cause cancers." (PMID 33623049, 2021). "Thus, the protective role of BRCA1 against oxidative stress, in combination with the oxidative DNA-damaging ability of estrogen metabolites, may partially explain the specificity of BRCA1- and BRCA2-mutant cancers in the breast and ovary, where estrogen levels are relatively high." (PMID 33498875, 2021). "A genetic counseling toolkit enabling BRCA1/2 founder/recurrent variant testing at the POC may add significant value, especially when incorporating the assessment of critical co-morbidities impacting on cancer risk and the option for NGS in eligible BRCA1/2 founder variant-negative cases." (PMID 34660253, 2021). "Thus while USP28 is elevated in BRCA1 mutant cancers, we could not detect its regulation directly downstream of BRCA1." (PMID 34465787, 2021). "The overexpression of wild type, but not the cancer-associated mutant form, of BRCA1 was shown to significantly reduce the cellular levels of ROS and protein damage caused by H2O2, whereas the knockdown of BRCA1 increased the ROS levels in MCF-7 and MCF-10A cells." (PMID 33498875, 2021).
cancer (continued). "In addition, cancer cells lacking the exon 11 of BRCA1 promoted partial PARPi resistance." (PMID 32563252, 2020). "Furthermore, a common Ashkenazi founder PV consisting of a BRCA1 duplication named 5382insC (HGVS nomenclature: c.5266dupC; p.Gln1756Profs) has been mainly observed in some families from the North-eastern coast of Sicily belonging to the city of Messina (11 individuals, including 6 cancer patients)." (PMID 32380732, 2020). "Soon after the discovery of BRCA1 and BRCA2 over 20 years ago, it became apparent that not all hereditary breast and/or ovarian cancer syndrome families were explained by germline variants in these cancer predisposing genes, suggesting that other such genes have yet to be discovered." (PMID 32726901, 2020). "However, the applicationof SL modulators still has a long way to go, as not all cancer subtypeshave clearly defined deficiency, such as has been seen with the applicationof PARP1 and BRCA1/2 inhibitors or the 29 clinical trials currentlyinvolving ATR inhibitors." (PMID 33135887, 2020). "The detection of BRCA1/2 reversion mutations during the natural history of HGSOC highlights how the loss of BRCA1/2 function and its associated DNA-repair defect seem to be required only for initiation of tumorigenesis and not needed for maintenance of the cancer phenotype." (PMID 32455819, 2020). "Notably, when STRING network analysis was used to investigate functional interactions, this revealed a DDR cluster that included BRCA1 and BRCA2, as well as their interacting tumour suppressor partners PALB2 and BAP1, two cancer-associated DDR genes not previously indicated as G4 ligand sensitisers." (PMID 31287417, 2019). "Assuming methylation of a small fraction of normal (including ovarian tissue) BRCA1 alleles to be associated with an OR for HGSOC of 2.0, such a finding should indicate 50% of the cancers may arise from unmethylated cells (like in an individual not carrying any BRCA1 methylated allele)." (PMID 31225507, 2019). "This showed that BRCA1-KO fibroblasts have a normal karyotype that is not changed following cancer EVs treatments and rules out the possibility that the observed effect was secondary to the presence of cancer cells carried over from conditioned media or patients’ sera." (PMID 31200749, 2019). "In addition, no DCIS was observed in BRCA1-positive cancers." (PMID 30820924, 2019). "The existence of cancer cases with similar somatic mutation spectra but no BRCA1/2 mutations raises the possibility that these carry mutations in genes of similar function and therefore may also benefit from treatments designed for BRCA mutant cancer." (PMID 31727117, 2019). "Therefore, BRCA1/2 testing is no longer sufficient to rule out the contribution of genetic factors to the cancers and it is possible that some of the patients for which no BRCA mutation was identified are carriers of a deleterious variant in another susceptibility gene or genes." (PMID 30400234, 2018). "Fifty percent of BRCA1/2 positive women diagnosed with breast cancer had no known immediate family history of cancer, indicating family history alone may not be enough to determine appropriate testing (Shkedi‐Rafid, Gabai‐Kapara, Grinshpun‐Cohen, & Levy‐Lahad, 2012)." (PMID 30152102, 2018). "Thus, combining PARP1 and RAD52 inhibitors to treat BRCA1 or BRCA2 mutant cancers might provide little or no therapeutic gain, and might increase normal tissue toxicity." (PMID 29145865, 2017). "Furthermore, our result suggests that other four targets (ARF, Rb, MMP, and BRCA1) could be potential targets for cancer reversion, even though they have not been previously elucidated." (PMID 28381275, 2017). "Though a regulation between BRCA1 and ER-α has been reported earlier and has been hypothesized as one of the causes for predisposition of BRCA1 mutated cancers to breast tissue, the tumorigenic effect could not be attributed to ER-α as most of the BRCA1 defective cancers are also triple negative." (PMID 28869585, 2017).
cancer (continued). "However, the uncomplicated co-segregation pattern seen in BRCA1 and BRCA2 families, where (almost) all BC patients carry the predisposing mutation and where mutation carriers have a high risk to develop cancer (typical for high penetrant monogenic diseases), is not found in CHEK2 families." (PMID 28649653, 2017). "Hence, upregulation of the DNA repair capacity of the cancer cell might represent a mechanism used to overcome the lack of a BRCA1-dependent repair mechanism." (PMID 25416589, 2014). "Thus alternative mechanisms may contribute to the lethal activity of PARP inhibitor in cancer cells lacking BRCA1." (PMID 25026298, 2014). "Although the interactive regulation between Aur A/B and BRCA1/2 may lie in different pathways such as proteolysis as we reported, this study may have provided some novel insights that the negative interplay between Aur A/B and BRCA1/2 plays an essential role during cancer development." (PMID 24775809, 2014). "We believe that methods for stratifying the likelihood of carrying a BRCA1 and BRCA2 mutation that is independent of family history are important, particularly in the Asian context, because the familial and social stigma associated with cancer makes accurate family-history reporting challenging." (PMID 23116406, 2012). "Moreover, PC families with BRCA1/2 and CDKN2A mutations were not excluded from the study; these families may have greater familiarity with cancer screening tests and their attitudes may differ in important ways from other PC family members." (PMID 22738386, 2012). "There may be mechanisms other than LOH or methylation by which the wt BRCA1 allele is inactivated in BRCA1-associated cancers which were not examined in this study (for example, somatic mutation of the second allele elsewhere in the BRCA1 gene or ID4 modulation of BRCA1 expression)." (PMID 21080930, 2010). "Identifying underlying mechanisms for effects of BRCA1/2 on non-cancer mortality, if the finding is confirmed, could lead to a better understanding of the biological basis through which the BRCA1/2 genes exert their impact on cancer risks as well as on other non-cancer conditions." (PMID 19277124, 2009). "Most importantly, genetic and pharmacologic inhibition of the GSK3B-53BP1 signaling axis dramatically enhances the cytotoxic response of cancer in vitro and in vivo to PARP inhibitors (PARPi) independent of BRCA1 status." (PMID 41243969, 2025). "These cells do not exactly resemble the heterozygous cells in BRCA1 carriers, because most BRCA cancer cells show LOH and other genomic alterations." (PMID 41283387, 2025). "Pol θ has been shown to conduct microhomology-mediated end-joining (MMEJ) (also known as theta-mediated end-joining or TMEJ) in the absence of functional BRCA1 and/or BRCA2 in cancer cells." (PMID 38666816, 2024). "The diagnostic process of women affected by breast cancer on a hereditary basis involves a first-level analysis of BRCA1 and BRCA2 genes and, if negative and clinically indicated, a second-level analysis of other cancer genes, including MUTYH." (PMID 38790183, 2024). "Our pan-cancer association analysis did not reveal enrichment of AM-1882 sensitivity with other cancer gene alterations (for example, CCNE1, RB1 or BRCA1)." (PMID 38151625, 2024). "We lacked specific cancer incidence data following RRSO and/or RRM for non-BRCA CSG carriers and assumed these were similar to BRCA1 and BRCA2 estimates." (PMID 38334999, 2024). "Regarding the role of FOXP3 in DNA repair, in cancer cells, the absence of FOXP3 enhances the homologous recombination (HR) pathway by activating BRCA1 expression." (PMID 39446493, 2024). "Compared with BRCA1/2 P/LPVs, non-BRCA P/LPVs exhibited different personal and family histories of cancer and molecular subtype distributions." (PMID 37096751, 2023).
cancer (continued). "Evaluation by logistic regression showed that the occurrence of side effects was not affected by PV/LPV gene (BRCA1 or BRCA2), gender, race, age or history of cancer." (PMID 37046302, 2023). "The true BRCA1/2 PV prevalence rate in an unselected NL population remains unknown; if estimated at approximately 1:137, then a population-based ascertainment regardless of cancer diagnosis would be expected to identify >3500 individuals rather than the 276 observed." (PMID 37887578, 2023). "The incidences of BRCA1 and BRCA2 carriers among relatives with 1, 2, and ≥3 cancer types were significantly higher than non-carriers." (PMID 36861435, 2023). "Eliminating family cancer history data did not reduce the performance of DrABC, with AUCs of 0.72 in predicting GPVs in any CPG, 0.75 in predicting GPVs in BRCA1/2, and 0.52 in predicting GPVs in other CPGs." (PMID 35209950, 2022). "One of the biggest limitations that remains is that large datasets of BRCA1- and BRCA2-mutant cancer patients treated with PARPi are not yet broadly available." (PMID 36568963, 2022). "Despite the modest sample size, we observed signficantly higher pCR rates in patients with BRCAmut cancers, but not BRCA1meth cancers, than in those with either BRCA1 and BRCA2 proficient cancers (P = 0.033)." (PMID 35857626, 2022). "There is a lot of research on the psychological determinants of the motivations of women to engage in cancer-preventive behaviors and specifically in BRCA1- and BRCA2-related cancer prevention, but there is still not enough information on men’s motivations." (PMID 35303741, 2022). "Twelve patients (3.7%) had a second primary cancer, with breast being the most common second cancer in BRCA2 carriers (41.7% vs. none in BRCA1 carriers, P = 0.007)." (PMID 34575694, 2021). "Genetic studies of the FC population have helped validate the role of rare potentially PVs in BRCA1 and BRCA2 in cancer syndrome families, sporadic cancer cases regardless of family history of cancer, and the general population." (PMID 34298626, 2021). "However, these deletions, which usually contain BRCA1, NBR2, BRCA1P1, and NBR1 genes, are not restricted to the NBR2 gene, and further studies are needed to confirm whether a specific deletion of the NBR2 gene determines cancer susceptibility." (PMID 34926299, 2021). "When VARDI and his colleagues treated cancer cells with genistein and daidzein, EPHB2 and GSTP1 methylation was down-regulated, while BRCA1 methylation was not affected." (PMID 34235089, 2021). "As pathogenic BRCA1 variants located in the RING domain disrupt BARD1-BRCA1 interaction, it was hypothesized that variants in BARD1 may also affect this interaction, thereby making BARD1 an attractive candidate to pursue in BRCA1 mutation negative cancer families." (PMID 32726901, 2020). "Across four cancer cell lines, increased ROS due to RAD51 depletion correlated with reduced cell numbers, although that was not paralleled in BRCA1-depleted cells." (PMID 32572160, 2020). "BRD4 inhibition induces HR deficiency independent of the BRCA status by impairing CTIP, BRCA1, and RAD51 expression, inducing DNA damage and eventually resulting in mitotic catastrophe in various cancer cell lines and PDX models." (PMID 32029455, 2020). "Six of the eight patients reported a family history of BC and other malignancies, whereas the patients carrying a BRCA1 exon 21 deletion and a complete BRCA2 deletion were not aware of any cancers in the family." (PMID 32375709, 2020). "Although previous cancer research showed that the majority of BRCA1 proteins form a heterodimer with BARD1, BARD1 did not colocalize with BRCA1 in tau aggregates in the AD, PiD, and PSP brain samples." (PMID 31861888, 2019). "Regarding BRCA1 and BRCA2, both of these genes showed similar strong positive correlations with UBE2C in different cancers, but a negative correlation was observed for BRCA1 in THCA and for BRCA2 in TGCT." (PMID 31067633, 2019).